INS (insulin)
Diseases named in the same sentence as INS in open-access papers (continued):
Sharing a sentence is not in itself a finding about the gene and the disease.
tumor (continued). "Calcium antagonists, (verapamil, D-600 and trifluoroperazine) and calcium ionophores (A23187 and Br-X537A) failed to modify insulin release or 45Ca uptake by each of the two tumours tested." (PMID 2825749, 1987). "Addition of verapamil to the cultures inhibited insulin output from one tumour, but mannoheptulose or diazoxide were without effect." (PMID 2825749, 1987). "Both blood glucose and plasma insulin levels were reduced in mice bearing the MAC16 tumour and this was not significantly altered by feeding the high fat diets." (PMID 3620317, 1987). "The management of the diabetic state did not influence the incidence of tumours, but insulin appeared to enhance tumour growth." (PMID 145871, 1977). "Both the number of cells containing insulin or GLP-1R, as well as their appearance in clusters, may occur more frequently than our data describe, because there may be clonal expansions in other parts of the tumours than those we have investigated." (PMID 41488993, 2026). "Both insulin-producing and GLP-1R-producing cells show clustering, and we find clonal expansion, which may give a greatly increased number of such cells in parts of the tumours." (PMID 41488993, 2026). "Insulin, C-peptide, adiponectin, and C-reactive protein (CRP) were selected to capture participants’ overall insulin sensitivity and inflammation profiles before and after the intervention, and serum PSA changes were investigated as a marker of tumor progression." (PMID 41546786, 2026). "Further insulin has been injected in very high concentrations subcutaneously for over 100 years in hundreds of millions of people without a single report of an injection‐site neoplasm." (PMID 40035222, 2025). "While it is known that CMV infection disrupts the normal intermediary metabolism on cellular level by modifying glucose and glutamine metabolism in a manner reminiscent of tumor cells, there is no established association between active CMV infection and insulin or glucose levels in vivo." (PMID 39691830, 2025). "Also, the functional character of the tumor was analyzed, with the tumor cells being positive for insulin and negative for glucagon." (PMID 39941267, 2025). "Finally, studies show that KDs help avoid high blood glucose and insulin levels in response to treatment with PI3K, AKT or mTOR inhibitor (the so-called insulin-feedback) and cooperate with these agents in achieving optimal tumor growth control." (PMID 39064705, 2024). "Collectively, ketogenic diets’ roles in anti-tumor therapy remain generally unclear, however, our intervention demonstrated that a supervised ad libitum WFKD consumed for three months can significantly improve insulin sensitivity and mitigate common side-effects induced by anti-tumor medication." (PMID 38166036, 2024). "In adults, INSR-B is expressed predominantly in insulin-targeted tissues, for example, muscle, adipose tissue, and the kidney, whereas INSR-A is expressed mainly in tissues of the embryo and fetus, the central nervous system, hematopoietic cells, and tumor tissues." (PMID 38392069, 2024). "To confirm that the observed growth inhibition of hypoxic tumors stems from lower available glucose rather than lower insulin or a modulation of the immune response mediated by the glucose consumption-dependent N-glycosylation, we replicated the oxygen-starved tumor microenvironment in vitro." (PMID 39574543, 2024). "The pivotal function of IGFBP3 in the insulin signaling axis may account for its regulatory role, representing a novel contributory mechanism to the tumor suppressor effect of ULK2 that is independent of its involvement in autophagy control." (PMID 38952983, 2024). "Moreover, we showed an association between the lack of GLP-1R expression and a larger tumour diameter and weaker insulin staining." (PMID 37894845, 2023).
tumor (continued). "Elevated insulin levels may encourage cell growth and division while affecting estrogen synthesis, metabolism, and signaling pathways, with increasing IGF-1 levels, which promote tumor growth and dissemination." (PMID 37957709, 2023). "Furthermore, KIAA1324 has been reported to counteract insulin signaling by interacting with insulin receptor (INSR) and insulin-like growth factor 1 receptor (IGF1R) and inhibit cell proliferation, supporting the tumor-suppressive role of KIAA1324." (PMID 37612293, 2023). "Patients consuming the KD with chemotherapy were found to have reduced tumor sizes by an additional 21mm, lower cancer staging, increased anti-tumorigenic factors of IL-10, reduced factors that promote angiogenesis such as TNF-alpha, insulin, and IGF-1, and a higher survival rate." (PMID 37937022, 2023). "While the immune cell intrinsic dysfunction caused by IR prior to PDAC remains to be fully understood, these studies suggest that insulin-mTORC1 driven inhibition of autophagy and Akt-STAT3 activation may drive tumor immune suppression via action on adaptive and innate immune cells." (PMID 36992811, 2023). "The results of the current study demonstrated that 10-years continuous PEG treatment results in disease control in almost all acromegalic patients resistant to SRLs, with a prolonged beneficial impact on insulin, and lipid metabolism, without tachyphylaxis and negative effects on tumour growth." (PMID 36892739, 2023). "To test if fat body insulin signalling facilitates cachexia progression via TGF‐β signalling, we next activated insulin signalling via fat body expression of InRCA and simultaneously knocked down TGF‐β signalling via fat body expression of madRNAi in tumour bearing animals (QRasV12, scribRNAi)." (PMID 38014610, 2023). "To investigate whether the browning process improved metabolic health, we tested blood insulin, blood glucose, insulin tolerance, and glucose tolerance in tumor-bearing mice with or without mirabegron treatment." (PMID 37993438, 2023). "Indeed, insulin and IGF-1 play crucial regulatory roles in human growth and metabolism, and epidemiological evidence demonstrates that they can promote tumorigenesis and progression by augmenting tumor cell proliferation, migration, and angiogenesis." (PMID 35600387, 2022). "The Insulin signaling pathway in group 5 was found to mainly lead to activation of genes involved MAPK signaling and this trend converges with hypoxia signaling input, both leading to the production of VEGFB, VEGFA, PGF, growth factors known to be involved in angiogenesis and tumor invasion." (PMID 35568708, 2022). "Another study found that the differentiation therapy consisting of four compounds, dexamethasone, isobutylmethylxanthine (IBMX), indomethacin, and insulin, could induce adipogenic differentiation of DDLPS cells and inhibit tumor growth both ex vivo and in vivo." (PMID 36557266, 2022). "Using the standard dose of dapagliflozin employed in this study (2.5 mg/mg), we then demonstrated that it significantly lowered blood glucose and insulin concentrations, resulting in a reduction in tumor glucose uptake when administered acutely (without differences in body weight)." (PMID 35595952, 2022). "Tat-BECN1 increases the release of insulin in murine and human primary islets (Tat-BECN1 is also reported to reduce adenosine-stimulated insulin secretion in islets), the secretion of candidate protein biomarkers of tumor cell autophagy, and the production of monoclonal antibody in CHO cells." (PMID 36172279, 2022). "They found that the use of PI3K inhibitors in conjunction with a ketogenic diet inhibited the insulin feedback-induced activation of the mTORC1 pathway by lowering insulin levels, thereby enhancing the efficacy of PI3K inhibitors, resulting in an anti-tumor effect." (PMID 35600387, 2022).
tumor (continued). "In addition, hypoxic but not normoxic tumor exosomes enhance oxidative phosphorylation in BMDMs via the transfer of let-7a miRNA, suppressing the insulin-Akt-mTOR signaling pathway." (PMID 36224346, 2022). "In addition, reduced plasma insulin levels at advanced tumor stage had significantly improved in Rec-m, albeit not comparable to levels of GCV-m." (PMID 34669013, 2021). "SSTR5 is a predominant inhibitory receptor for glucose-induced insulin secretion and conveys most of the negative impacts of SSAs on glucose metabolism, but how this affects tumor proliferation is unknown." (PMID 35008325, 2021). "Targeting isoforms p110β and p110δ via RNAi could reduce AKT activation through IGF-I or insulin, indicating that both PI3K isoforms contributing to the upregulation of IGF-1R or IR in AML cells and improving the sensitivity of tumor cells to chemotherapeutical drugs." (PMID 33768092, 2021). "Both insulin and IGF-1 could act as growth factors for tumor cells." (PMID 33727597, 2021). "At a cellular level, activation of insulin/IGF signaling pathway has been hypothesized to contribute to tumor initiation and/or progression through tumor cell-specific mechanisms including the promotion of cell division, glucose metabolism and epithelial-to-mesenchymal transition (EMT)." (PMID 33604295, 2020). "Our results are consistent with the idea that low‐dose ACA improved survival without tumor suppression implicating its lifespan‐extending effect on improved insulin sensitivity while high dose ACA improved survival by a combination of its action on postprandial glucose/insulin levels and on tumors." (PMID 31903726, 2020). "Therefore, adherence to a diet with a low carbohydrate content might suppress tumor cell proliferation and regulate apoptosis via cell signaling pathways, the PI3K/Akt/Mtor and RAS/RAF/MEK/ERK sequences, which are insulin or IGF-Ι-dependent." (PMID 31831005, 2019). "However, long-term treatment with pioglitazone or metformin failed to enhance the tumor suppressor, cav-1, at high concentrations of glucose and insulin." (PMID 30729133, 2019). "For example, melatonin secreted from the pineal gland and insulin secreted from the pancreas both travel in the blood to reset peripheral clocks, and a lack of tumor vasculature may desynchronize tumor cells from surrounding tissue." (PMID 33089179, 2019). "However, the mechanisms undergirding insulin’s effect upon certain tumors have remained unclear, in part due to a lack of methods to assess tumor substrate preference and the impact of variations in hormones and substrates on tumor fuel preference." (PMID 31188872, 2019). "Next, we aimed to understand whether DNP exerted a direct effect on tumor growth or metabolism independent of insulin." (PMID 31867105, 2019). "In addition, the tumor-promoting protein kinase C activator PMA consistently enhanced insulin secretion, demonstrating the importance of the protein kinase C pathway in the regulation of insulin secretion." (PMID 30761839, 2019). "Similarly, tumor-bearing sedentary rats showed a reduction in insulin levels compared to sedentary rats without tumors (p < 0.0001)." (PMID 29867528, 2018). "This suggests a capacity of insulin signaling to guide tumor outcomes independent of body weight." (PMID 28959684, 2017). "For instance, the involvement of insulin and IGF-1 in colorectal carcinogenesis could have increased free IGF-I with concomitant changes of environment mitogenesis and anti-apoptosis in the cells favouring tumour formation." (PMID 28778191, 2017). "Whether PI3K-stimulating hypoglycemic agents (such as insulin, sulfonylureas, DPP4-inhibitors/GLP-1 agonist, or meglitinides) can be used without risk of tumor growth is another area in need of more research." (PMID 28856166, 2017). "Thus, the fact that members of an anti-tumor agent family decrease tumor growth is not definitive evidence for a role of insulin." (PMID 28060743, 2017).
tumor (continued). "Therefore, the increase in insulin and IGF1 levels, present in both obese and diabetic patients, may facilitate the EMT and tumor progression." (PMID 29383194, 2017). "Tumor cells were positive for chromogranin A and glucagon, while insulin staining was negative." (PMID 27769070, 2016). "However, the weight gain was neither correlated with altered non-fasting plasma glucose levels nor non-fasting plasma insulin levels in tumor-bearing mice." (PMID 27825136, 2016). "Overall, metformin benefits to breast cancer may be due to its role on cellular cycle and PI3K/Akt/mTOR signaling pathway and negative insulin effects on tumour development and growth." (PMID 27725832, 2016). "The negative immunoreactivity for insulin may indicate the production of precursor, or pro-insulin by tumour rather than insulin itself." (PMID 26911576, 2016). "These candidate biomarkers can include all members of the complex IGF system (both systemic and local/tumor expression levels) and markers connected to the IGF system, including the downstream signaling pathways and gene signatures indicative of increased tumor insulin/IGF-I activity." (PMID 27129151, 2016). "The tumour stained positively for gastrin, but not for insulin." (PMID 25755880, 2015). "However, in cachectic tumor-bearing mice, rosiglitazone treatment that was intended to restore peripheral insulin resistance did not affect tumor mass." (PMID 25807446, 2015). "This suggests that insulin glargine is not inert and may affect the intracellular signaling in the developing tumor." (PMID 25848982, 2015). "However, at 9 months of age, the exposed offspring examined in this study—regardless of tumor presence—exhibited body weights and serum glucose and insulin measurements at or below levels found in control animals." (PMID 24487385, 2014). "Indeed, the serum insulin- and IGF-1-lowering effects of metformin have been thought to explain why the administration of metformin suppresses tumor development or growth in multiple experimental models, including colon, hematopoietic, and mammary cancer models." (PMID 23986086, 2013). "Immunohistologic stains of the tumor for insulin, glucagon, and somatostatin were negative." (PMID 26425568, 2013). "Insulin, angiotensin-II and epidermal growth factor have been shown to up-regulate HIF in the presence of molecular oxygen and mTOR inhibition decreases tumour progression partially to decreased neo-vascularisation, indicating mTOR as a regulator of HIF by increasing its mRNA translation." (PMID 23758895, 2013). "Other studies suggest that metformin might delay the initial development of tumors by direct actions on the tumor cells themselves, even in animals that are not insulin-resistant." (PMID 23587167, 2013). "Thus, the anti-tumoral action of metformin is not precluded in PTEN+/−, HER2, and APCmin/+ mouse tumor models, in which insulin-related markers are not significantly attenuated by treatment with metformin." (PMID 23986086, 2013). "However, it is not clear how mitogenic effects of insulin and insulin analogs measured in vitro correlate with tumor growth-promoting effects in vivo." (PMID 24260289, 2013). "The tumor cells could have redifferentiated, developing the ability to secrete insulin, not present at time of resection." (PMID 26425568, 2013). "It was not clear whether the insulin analogue initiated the tumor or helped the growth of pre-existing malignant foci." (PMID 22870179, 2012). "Notably, tumor cell proliferation was positively correlated with serum visfatin and insulin concentrations, and tumor apoptosis showed a strong negative correlation with circulating visfatin and serum insulin concentrations." (PMID 23170114, 2012). "Therefore, we cultured tumour cell lines at physiological glucose concentrations (5.5 mM) and at high glucose (11 mM) with or without additional insulin (100 ng ml−1)." (PMID 21179032, 2011).
tumor (continued). "Thus, it may depend on the circumstances which variables - including blood glucose, insulin, lactate, IGF1, fat quality and ketone bodies - are the best predictors of and responsible for the anti-tumor effects of very low CHO diets." (PMID 22029671, 2011). "However, there are data from 20 years ago, describing the positive effects of glucose and insulin on the progression of tumours, without further identifying the genetic and molecular modifications." (PMID 21179032, 2011). "Boris Draznin focused on the fact that insulin- by increasing the amount of farnesylated Ras molecules- enhances the effects of growth factors such as IGF-1, and that hyperinsulinaemia thereby augments the mitogenic effects of growth factors (e.g. on tumour cells)." (PMID 21176129, 2010). "β-cell hyperplasia was also induced in Pdx1-tTA; tet-o-PyMT-IRES-Luc bitransgenic mice, and the insulin-expressing β-cell hyperplasia does not further progress to form frank neoplasms even after 1 year of oncogene activation and in Ink4a/Arf-null and Arf-null backgrounds." (PMID 19812721, 2009). "The cytokine did not modify the plasma levels of corticosterone and insulin in the tumour hosts." (PMID 10945502, 2000). "Insulin release from a clonal expansion, with or without GLP-1R stimulation, might cause hypoglycaemia, and increased levels of GLP-1R might induce less aggressive tumours." (PMID 41488993, 2026). "Notably, patients receiving insulin for glucose control likely have more advanced T2D, which could influence tumor progression irrespective of antiglycemic medication." (PMID 41178720, 2025). "Although our study may have had insufficient power to examine these associations, as these measurements were done only on a subset of mice, our results suggest that consuming a LoGI diet may not inhibit the insulin/IGF-1 pathway strongly enough to impact tumor growth." (PMID 38082056, 2024). "Tumours are termed functional if they are associated with secretion of specific hormones, including insulin, glucagon and VIP hormone, with some causing symptoms such as facial flushing, diarrhoea, while nonfunctional tumours may show no overt signs of hormone-associated disease secretion." (PMID 36362433, 2022). "Their findings also support our results, wherein we observed that in the tumour setting, SIRT6 over‐expression inhibited WNT4 expression in the skeletal muscle and downregulated circulating levels of WNT4, which might have contributed to maintain plasma insulin levels in Tu‐Sk.T6Tg mice." (PMID 34212132, 2021). "Therefore, the few negative tumours in our cohort may express INS and INS-IGF2 transcripts and corresponding polypeptides in other areas than we examined." (PMID 34170845, 2021). "Besides the undesired inhibition of insulin action in the liver, muscle and fat that results in metabolic toxicity and likely precludes their use at clinically effective doses, monotherapy against the IGF system may also downregulate anti-tumor immunity." (PMID 32512898, 2020). "Finally, we examined the potential impact of ketones themselves to alter MC38 tumor growth in vivo and found that chronic (4 weeks) ketone supplementation in drinking water had no impact on plasma glucose or insulin concentrations or on tumor size, despite doubling plasma β-OHB concentrations." (PMID 31867105, 2019). "Interfering with insulin signaling may slow tumor growth, while activation of the insulin receptor may promote tumor progression in murine models, although there have also been publications demonstrating the absence of an effect of insulin on tumor growth." (PMID 31867105, 2019). "Insulin binds to IGF-1 receptors and plays an important role in cell proliferation, apoptosis, and increased production of vascular endothelial growth factor, an angiogenetic factor that supports tumor growth and may play a role in the development and growth of HPs." (PMID 28127545, 2017).